BRD4 (bromodomain containing 4)
Diseases named in the same sentence as BRD4 in open-access papers (continued):
Sharing a sentence is not in itself a finding about the gene and the disease.
leukemia (continued). "Among them, the effect of I-BET151 on BRD9 may be indirect because BRD9 and BRD4 form a complex.I-BET151 selectively inhibits leukemia mouse models and mixed-lineage leukemia (MLL) primary patient samples, and its half-life is significantly longer than that of similar BET inhibitors (JQ1, I-BET762)." (PMID 34540687, 2021). "Thus, acquired resistance to WEE1 inhibition may be reversed by HDAC or BRD4 inhibition in leukemia cells." (PMID 32195191, 2020). "CDK7 has been shown to play an important role in regulating the transcriptional activity of enhancers, which motivated us to test the idea that CDK7 inhibitors (e.g., THZ1) might synergize with BETi to suppress BRD4-independent enhancers to overcome BETi resistance commonly seen in leukemia." (PMID 32029739, 2020). "Indeed, the active P-TEFb-Brd4 complex has been linked to AML and CML, while multiple SEC components are direct targets of MLL-fusion proteins that are linked to various forms of leukemia." (PMID 25053741, 2014). "dBET1, a first-generation PROTAC BET degrader, induces selective degradation of BRD4, resulting in robust MYC suppression and apoptosis in leukemia models." (PMID 41335282, 2025). "It specifically induced BRD4 degradation with a DC50 of 0.43 μM in SUM149 cells, and it delayed the progression of leukemia in mouse models of the disease." (PMID 38389844, 2024). "In leukemia, NSUN1 specifically interacts with BRD4 and directly binds to the CTD‐S2P of RNA polymerase II (RNA‐pol II)." (PMID 39445003, 2024). "In 5‐azacytidine (5‐AZA)‐resistant leukemia cells, a unique NSUN1/BRD4/RNA‐pol II CTD‐S2P complex is formed, mediating the development of 5‐AZA‐resistant chromatin structures and contributing to 5‐AZA resistance in leukemia." (PMID 39445003, 2024). "This compound demonstrated significant efficacy in terms of inhibiting BRD4, with an IC50 value of 9.4 nM, and effectively suppressed cell proliferation in the BRD4-sensitive RS4;11 leukemia cell line, with an IC50 value of 27.6 nM." (PMID 38389844, 2024). "I-BET 151 induced G1 phase cell-cycle arrest and apoptosis for mixed lineage leukemia (MLL), achieved by reducing the binding of BRD4 to the promoter regions of MYC, BCL2, and CDK6." (PMID 38539460, 2024). "NSUN1 can participate in gene expression regulation through bromodomain-containing protein 4 (BRD4) and Pol II recruitment in 5-AZA-resistant leukemia cell lines." (PMID 37476573, 2023). "I-BET151 is a compound that inhibits the bromodomain and extra terminal (BET) protein BRD4 and was previously reported to be particularly efficient on KMT2A-r leukemias, confirming the robustness of our high-throughput screening." (PMID 35153769, 2021). "Our study demonstrated that RNA cytosine methyltransferase NOP2/NSUN1 and NSUN2 interact with BRD4 and the elongating form of RNAP (CTD-S2P) to form a transcriptionally active chromatin structure in leukemia cells." (PMID 33922187, 2021). "This offers an alternative approach to reactivating anti-cancer targets of BRD4 than seen in other cancer types, such as in AML or leukemia, where β-catenin mediated transcription of MYC compensates for BRD4 to drive BETi resistance." (PMID 33712563, 2021). "It had a sub-micromolar DC50 value for BRD4 degradation and significantly inhibited proliferation of MV4;11 leukemia cells in vitro and in a mouse model." (PMID 32404196, 2020). "In leukemia cells, NSD3S has been shown to be essential for cancer progression by bridging the interaction between the bromodomain containing protein 4 (BRD4) and chromodomain helicase DNA binding protein 8 (CHD8)." (PMID 31638140, 2020). "Another approach is the inhibitory targeting of proteins such as BRD4 (bromodomain-containing protein 4) recruited to the regulatory elements of the MYC gene, which can switch off the MYC-dependent leukemia sustainment program." (PMID 33302406, 2020).
leukemia (continued). "The ability of MLL-FPs to reprogram HSPCs toward leukemia requires the involvement of multiple chromatin effectors, including the histone 3 lysine 79 methyltransferase DOT1L, the chromatin epigenetic reader BRD4, and the super elongation complex." (PMID 31157223, 2019). "Our results indicate that the BRD4-dependent transcriptional program is a defective pathway in MDS and AML pathogenesis and its inhibition induces apoptosis of leukemia cells, which is enhanced in combination with HMA or an ATR inhibitor." (PMID 30761268, 2019). "Inhibitors of BRD4 had efficacy in MLL-AF9,NrasG12D model and on a variety of leukemia cell lines, with MLL-r leukemias preferentially affected." (PMID 28232907, 2017). "Accordingly, inhibition of DOT1L led to dramatically decreased binding of BRD4 to chromatin, and the combination of a bromodomain inhibitor and a DOT1L inhibitor was synergistically active against MLL-r leukemias both in vitro and in vivo." (PMID 28232907, 2017). "Functional analysis showed that the inhibition of proline hydroxylation pathway significantly reduced the proline hydroxylation abundance on Brd4 and affected Brd4-mediated transcriptional activity as well as cell proliferation in AML leukemia cells." (PMID 27764789, 2016). "Although the detail mechanisms of hydroxylase-regulated Brd4 transcriptional activities require further investigation, it demonstrates that the oncogenic proline-hydroxylation-dependent pathways may potentially serve as new targets for the development of therapeutic strategy in leukemia." (PMID 27764789, 2016). "Preclinical evaluation of the Brd4 inhibitor JQ1 in AML demonstrated potent in vitro and in vivo inhibition of leukemia proliferation and elimination of leukemia-initiating cells, likely via suppression of MYC." (PMID 24672775, 2014). "The inhibition of BRD4 with BET inhibitors disrupts the transcriptional machinery at the level of super-enhancers, which are crucial for maintaining the high expression of MYC and other oncogenes in KMT2Ar leukemias." (PMID 39682203, 2024). "Although genomic SPOP mutation is rarely observed in human leukemia, our preliminary data identified SPOP as an essential gene in BETi-resistant leukemia cells; however, BRD4 and MYC were not direct substrates." (PMID 37036970, 2023). "The well-established therapeutic target BRD4 is a member of the bromo- and extra-terminal domain (BET) family, which activates MYC’s enhancers, thereby maintaining its high oncogenic overexpression in KMT2A-r leukemia and other cancers." (PMID 37036970, 2023). "Combination therapy with the BRD4 inhibitor ABBV-744 and the GSK3 inhibitor CHIR-98014 considerably suppresses KMT2A-rearranged leukemia progression in patient-derived xenograft models in mice, confirming ABBV-744 and CHIR-98014 combination therapy as an effective therapeutic strategy." (PMID 38135679, 2023). "In SUP-T1 cells, apart from downregulation of the known BRD4 targets like Myc, Bcl-2, Bcl-XL, and Mcl-1, treatment with ARV-825 substantially decreased the expression of key molecules involved in leukemia persistence, such as HES1 (a direct target of Notch1), PI3K/AKT pathway proteins, and CD44." (PMID 35173274, 2022). "The resulting degrader 80 displayed substantial degradation potential towards BRD4 and could also inhibit the growth of tumor as evidenced in an in vivo murine hind-limb xenograft model with human MV4-11 leukemia cells." (PMID 33840388, 2021). "Our recent study demonstrates that NSUN1 expression is elevated in leukemia cells, and NSUN1 interacts with BRD4 to recruit elongating RNA polymerase II (eRNAPII) to nascent RNA, forming an active chromatin structure and transcription complex that mediates drug resistance in myeloid leukemia." (PMID 33922187, 2021). "Similarly, persisters originating from T-cell acute lymphoblastic leukemia (T-ALL) rely on the chromatin modifier protein BRD4, consistent with the benefit of the BRD4 inhibitor JQ1 in primary human leukemias." (PMID 32365663, 2020).
leukemia (continued). "In human AML leukemia cells, the short form of NSD3 could be recruited by BRD4 to Myc enhancers and activate Myc expression." (PMID 32669118, 2020). "Indeed, inhibition of BRD4 results in notable anti-cancer effects in a variety of MYC-driven cancers, including leukemias, lymphomas, and multiple myeloma." (PMID 32796829, 2020). "Capitalizing on the CRISPR interference technology, we identified the second intron of IncRNA, PVT1, as a unique bona fide gained enhancer that restored MYC transcription independent of BRD4 recruitment in leukemia." (PMID 32029739, 2020). "To rule out the possibility that the observed inhibitory effect might arise from off-target effects of chemicals, we knocked down BRD4 and CDK7 individually or in combination with shRNAs in both human (K562 and Jurkat) and murine AF9 leukemia cells." (PMID 32029739, 2020). "Moreover, MLL-FPs are able to form a molecular complex with BRD4 (an epigenetic reader), PAFc and SEC to sustain the oncogenic expression of BCL2, CDK6, and MYC in MLL-r leukemias." (PMID 31157223, 2019). "They found that combined targeting of both DOT1L and BRD4 using SGC0946 (a small-molecule inhibitor of DOT1L) and I-BET, respectively, resulted in growth inhibitory synergy against MLL-r cell lines, primary human leukemia cells, and mouse leukemia models." (PMID 31157223, 2019). "Moreover, in vitro studies showed that BRD4 inhibition, combined with azacitidine or AZD6738, synergistically induced apoptosis of leukemia cells." (PMID 30761268, 2019). "Western blotting demonstrated a small increase (~1–2 fold) in the expression of total RNA-pol-II, CTD-S2P, CDK7, CDK9/P-TEFb, BRD4 and BRD2 in the 5-AZA-resistant M2AR and SCAR leukaemia cells compared to the original 5-AZA-sensitive OCI-M2 and SC leukaemia cells." (PMID 29563491, 2018). "Importantly, JQ1 and dominant-negative Brd4 mutants regulated the same set of target genes of c-Myc, a key regulator of the JQ1 response in leukemia cells." (PMID 28490802, 2017). "The essential role of BRD4 in cancer was first discovered by using a negative selection RNAi screening in a mouse model of MLL-rearranged leukemia." (PMID 29240787, 2017). "In addition, DOT1Li and BRDi are shown to be synergistic in treating MLL-rearranged leukemia, possibly due to functional collaboration between DOT1L and BRD4 at the highly transcribed super-enhancer genes." (PMID 29075615, 2017). "This in turn forms a docking site for BRD4 thereby facilitating the target gene expression and co-inhibition of DOT1L and BRD4 has been shown to act synergistically in targeting MLL-rearranged leukemias." (PMID 29240787, 2017). "Therefore, combining POL5551 with newer targeted agents, such as inhibitors of BRD4 or DOT-1L in MLL-R leukemias and phosphoinositide 3-kinase (PI3K) and mTOR inhibitors in hypodiploid ALL and Philadelphia chromosome-like ALL, may improve outcome in these high-risk pediatric leukemias." (PMID 26360610, 2015). "This simple, unifying mechanism is also supported by the observation that highly specific inhibitors that target the acetyl binding pocket of BRD4 disrupt activation of some MLL-FP target genes such as MYC, and impair the growth of a wide range of different MLL-FP-mediated leukemias." (PMID 24213472, 2012). "Moreover, whereas BRD4 inhibitors transitorily repressed MYC transcription in types of human leukemias regardless of their sensitivity, resistant cells exhibited a rapid restoration of MYC transcription." (PMID 36567628, 2023). "Moreover, Brd4/BET inhibition triggered terminal differentiation of AML blasts, inducing expression of myeloid differentiation marker while decreasing that of leukemia stem cell marker." (PMID 33594072, 2021). "Given that CDK7 inhibitors have been shown to suppress pro-oncogenic transcription by targeting enhancers in tumor cells, we envisioned that dual inhibition of BRD4 and CDK7 might synergize to suppress the growth of BETi-resistant leukemia cells to overcome resistance." (PMID 32029739, 2020).
leukemia (continued). "Likewise not known is how the BRD4 protein at the molecular level helps turn on Myc synthesis in MLL-AF9-driven leukaemia." (PMID 23303309, 2013). "Although several novel compounds, such as inhibitors of DOT1L, LSD1 and BRD4, are in clinical trials, there have been no effective treatments for MLL1-r leukemia." (PMID 35395864, 2022). "Consistent with the results from pharmacological inhibition using BETi and/or THZ1, we found that only the dual knockdown of BRD4 and CDK7, but not single-knockdown, substantially inhibited the growth of BETi-resistant leukemia cells (red/purple curves)." (PMID 32029739, 2020). "While BRD4 and the H3K79 methyltransferase DOT1L do not physically interact, studies in mixed lineage leukemia have suggested DOT1L methylates and establishes a chromatin state that is permissive for acetylation and BRD4 recruitment." (PMID 27698495, 2016). "Initially considered to work primarily through inhibition of BRD4 mediated MYC gene expression, the molecular mechanism is likely to be more complex than this as MYC expression cannot completely rescue the effect of the BET inhibitor JQ1 and some leukemias that express MYC are not sensitive to JQ1." (PMID 24213472, 2012).
acute myeloid leukemia (86 papers, 2013 to 2025). Acute myeloid leukemia (AML) is a group of neoplasms arising from precursor cells committed to the myeloid cell-line differentiation. "BRD4 is BET protein that is important for myc expression in acute myeloid leukemia (AML) as well as the expression of other driver mutations in additional malignancies." (PMID 28966805, 2017). "JQ1 effects in multiple myeloma and AML (acute myeloid leukemia) are associated with inhibition of a particular Bromodomain protein, BRD4." (PMID 24796395, 2014). "For example, in acute myeloid leukemia (AML), intrinsic resistance to BET inhibition results in activation of a c-MYC enhancer that compensates for the loss of BRD4 by utilizing WNT signaling to drive oncogenesis." (PMID 38654040, 2024). "For instance, super-enhancers inside the MYC locus are connected to BRD4 in several malignancies, including acute myeloid leukemia (AML) and multiple myeloma." (PMID 37509171, 2023). "Evaluation of this PROTAC, HBL-4, in a model of acute myeloid leukemia (AML) demonstrated rapid degradation of both BRD4 and PLK1." (PMID 37174744, 2023). "BRD4 inhibitors have been shown good anti-tumor effects in a variety of tumors, including acute myeloid leukemia and multiple myeloma, and a large number of BRD4 inhibitors are currently in clinical trials." (PMID 36339620, 2022). "BRD4 was identified as promising target structure in acute myeloid leukemia as inhibition of BRD4 using shRNA or a small molecule inhibitor resulted in anti-leukemic effects in vitro as well as in vivo." (PMID 34333666, 2021). "Because of its important role in regulating essential oncogenes, BRD4 has become an important target in a variety of cancers, including acute myeloid leukemia (AML), multiple myeloma (MM), and prostate cancer." (PMID 34488823, 2021). "BRD4 has been proposed to be a critical chromatin regulator that maintains disease progression in acute myeloid leukemia (AML)." (PMID 34926269, 2021). "Suppression of BRD4 led to anti-leukemic effects in acute myeloid leukemia (AML) mouse models and revealed a potential epigenetic target for AML." (PMID 33879235, 2021). "GNE-987, containing a potent tetracyclic BRD4 inhibitor, exhibited extremely high activities in degradation of BRD4 and growth inhibition of acute myeloid leukemia EOL-1 cells in low pM levels." (PMID 32404196, 2020). "BET bromodomain proteins have been therapeutic targets of substantial interest since the discovery that BRD4 is essential for disease maintenance in acute myeloid leukemia nearly 10 y ago." (PMID 33046654, 2020). "There is limited but growing evidence that BRD4 interacts with HIFs and modulates HIF activities to develop BRD4 as a reliable therapeutic target in multiple cancers, including acute myeloid leukemia, multiple myeloma, and Burkitt’s lymphoma." (PMID 33109235, 2020). "Unbiased genetic screening for a variety of cancers has shown that BRD4 is critical for cell survival and a promising anticancer target, such as acute myeloid leukemia, glioblastoma and lung adenocarcinoma." (PMID 32099528, 2020). "These include the discovery of BRD4 (belongs to bromodomain family) inhibitors as therapeutics for acute myeloid leukemia, other malignancies and inflammatory diseases." (PMID 25962125, 2015). "Evidence of BRD4 dependency in human malignancies was later extended to acute myeloid leukemia (AML)." (PMID 25072021, 2014). "The subsequent identification of Brd4 as an important maintenance gene in acute myeloid leukemia (AML) fueled further interest in Brd4 as a cancer target." (PMID 25242322, 2014). "BRD4 and BRD9 have been reported to co-localize at the Myc super enhancer in the mouse cell line model for acute myeloid leukemia, suggesting that recognition of acetylated BRD4 may be a common mechanism of GBAF complex recruitment." (PMID 30510198, 2018).